TMPRSS2 (transmembrane serine protease 2)
Diseases named in the same sentence as TMPRSS2 in open-access papers (continued):
Sharing a sentence is not in itself a finding about the gene and the disease.
infection (continued). "Enzyme kinetic measurements with recombinant TMPRSS2 confirmed that both cleavage sites of SARS-CoV-2 S could be efficiently processed by TMPRSS2, although furin has been shown to be responsible for the cleavage of the S1/S2 site during infection." (PMID 39599912, 2024). "The expressions of both ACE2 and TMPRSS2 were not affected by infection or procaine treatment." (PMID 37834031, 2023). "Moreover, Caco-2 cells naturally express ACE2 and TMPRSS2, and SARS-CoV-2 infects and replicates significantly more efficiently than in the lung cell line Calu-3 with the same multiplicity of infection." (PMID 37748810, 2023). "We extended our observations to Calu-3 cells, a lung epithelial cell line that expresses both ACE2 and TMPRSS2, and observed a dose-dependent inhibition of SARS-CoV-2pp infection with an IC50 of 1.77μM compared to 0.23μM for Vero-TMPRSS2 cells and no detectable effect on cell viability." (PMID 37134108, 2023). "For example, the decrease in TRPRSS2 activity in the PG/VG Cultex group was accompanied by an increase in infection, which may have occurred by a mechanism not involving TMPRSS2, such as endocytosis." (PMID 37037851, 2023). "Little efficacy has been demonstrated to date in such strategies, prompting speculation that TMPRSS2 may facilitate infection without being an absolute requirement for coronavirus and influenza viruses." (PMID 37987478, 2023). "The SARS-CoV-2 S protein is necessary for infection, and this is related to its binding on the angiotensin-converting enzyme (ACE)-2 receptor expressed by host cells, and the receptor-mediated virus entry depends on a serine protease, transmembrane serine protease 2 (TMPRSS2)." (PMID 37371134, 2023). "Infection by the SARS-CoV-2 starts from the cellular entry of the virus through the interaction between the viral Spike (S) protein with its cell surface receptor ACE2 (angiotensin-converting enzyme 2) and priming of the S protein by the cellular protease TMPRSS2 (transmembrane serine protease 2)." (PMID 37642993, 2023). "TMPRSS2 expression has an even broader distribution implicating that ACE2, rather than TMPRSS2, may be a limiting and major factor for viral entry at the early stage of the infection." (PMID 37646038, 2023). "However, it does not inhibit infection of TMPRSS2-expressing cells because virus entry is independent of CatL." (PMID 37047226, 2023). "This polarity of infection could not be explained by polarized expression of ACE2 or TMPRSS2 at the basolateral side as both molecules were rather found at the apical side of HIBCPP cells." (PMID 37875964, 2023). "At 48 hours post-infection, we detected robust co-staining of SARS-CoV-2 N positive and human IgG patches (reminiscent of CB6) on Vero E6 cells (top); effect of CB6 on SARS-CoV-2 syncytia formation was further enhanced when SARS-CoV-2 infected Vero E6 cells over-expressing the TMPRSS2 (bottom)." (PMID 37948454, 2023). "Furthermore, infection is facilitated by TMPRSS2, and we did not see any evidence for expression on neutrophils by RNA and protein (data not shown)." (PMID 37006263, 2023). "We screened the antiviral activity of the crude methanolic extracts at a concentration of 25 μg/mL by quantifying the infection of HCoV-229E-Luc in Huh-7 cells, whether they expressed the TMPRSS2 protease or not." (PMID 38068938, 2023). "During the viremia phase, early infection by the virus is initiated in the epithelial cells of the nasal cavity and the larynx, the major site of virus entry, through angiotensin-converting enzyme 2(ACE2) receptors with the help of transmembrane serine protease 2 (TMPRSS2)." (PMID 36232549, 2022). "HAI-2 reduced the growth of influenza virus and infection of human parainfluenzavirus-1 in both TMPRSS2-expressing and TMPRSS2-negative cells, indicating that additional proteases involved in viral entry may be inhibited." (PMID 35163273, 2022).
infection (continued). "Indeed, when TMPRSS2 and IFITM3 were co-expressed in 293T-ACE2 cells, infection of SARS-CoV-2 S-pseudotyped viruses was less inhibited by IFITM3 compared to that in cells not expressing TMPRSS2." (PMID 36423162, 2022). "It is therefore plausible that women infected early in pregnancy could potentially pass SARS‐CoV‐2 to the fetus, but with low fetal infection rates due to the minimal ACE2 and TMPRSS2 co‐expression in the fetal tissues studied, including the gastrointestinal tract, early in pregnancy." (PMID 34735736, 2022). "Interestingly, although full-length LF was not able to block TMPRSS2 activity, it prevented infection of Vero cells by ≈38% when used at 40 μg/mL, and seemed even more potent in Calu-3 cells, where ≈60-70% inhibition was observed." (PMID 36081512, 2022). "We conclude that different proteases, including TMPRSS2, ADAM10, ADAM17, and potentially others, may prime S2 and, thus, facilitate: (i) infection through the fusion of the SARS‐CoV‐2 virus with host cells, or (ii) syncytia formation of S‐expressing SARS‐CoV‐2‐infected cells with host cells." (PMID 35527514, 2022). "The inhibitor appears to specifically block SARS-CoV-2 entry by the endosomal pathway, as it was highly effective on VeroE6 cells that lack TMPRSS2 but failed to inhibit infection of Calu-3 cells that expresses TMPRSS2, which enables SARS-CoV-2 to fuse at the plasma membrane." (PMID 36298757, 2022). "However, the low infection rate of SARS-CoV-2 in hESC suggested that only a small part of hESC could be infected, which was consistent with low ACE2 and TMPRSS2 expression in hESC." (PMID 35755832, 2022). "We hypothesized that the modest degree of TMPRSS2-dependent enhancement (3.4×) for Delta and a complete lack of enhancement for Omicron over a single infection round might relate to the overexpression of ACE2 in this system." (PMID 35104837, 2022). "We hypothesised that the modest degree of TMPRSS2 dependent enhancement (3.4x) for Delta and a complete lack of enhancement for Omicron over a single infection round might relate to the overexpression of ACE2 in this system." (PMID 35075452, 2022). "However, immunofluorescence microscopy showed that only a small portion of hESCs were infected and the infection rate of SARS-CoV-2 in H1 and H9 hESCs was 7.68‰ and 8.24‰, respectively, consistent with the relatively low expression levels of ACE2 and TMPRSS2 in hESCs." (PMID 35755832, 2022). "As expected, we could not detect progeny viral titers in the A549 cell lines lacking robust levels of endogenous ACE2 (parental A549 cells and A549-TMPRSS2 cells stably expressing TMPRSS2), whereas ACE2 overexpression allowed for a successful infection at MOI 0.01." (PMID 35013790, 2022). "Coagulation factor Xa (fXa) and thrombin (thr) are widely expressed in pulmonary tissues, where they may catalyze, together with the transmembrane serine protease 2 (TMPRSS2), the coronaviruses spike protein (SP) cleavage and activation, thus enhancing the SP binding to ACE2 and cell infection." (PMID 36016352, 2022). "In our study, follicular cells, GCs and CCs have an interindividual variability and a very low expression of TMPRSS2, pointing to the fact that other proteases may have the main function, and TMPRSS2 is not solely necessary for the infection." (PMID 35563737, 2022). "This is in line with recent reports, suggesting that ACE2 and TMPRSS2 expression might be prerequisite for BSG and NRP1 to exert their infection-potentiating activity Interestingly, previous studies have shown that ACE2 expression is regulated by IFNα and IFNγ signalling." (PMID 35837388, 2022). "Indeed, SIRPA only restricted infection of 293T-ACE2 cells, in which trafficking to the cathepsin-containing acidic endosomes is required for entry, but not of Calu-3 lung epithelial cells, which express both ACE2 and TMPRSS2 on the surface." (PMID 34097709, 2021).
infection (continued). "There is only one study in which absence of the viral host cell factors ACE2 and TMPRSS2 expression on human umbilical cord blood‐derived MSCs is claimed, but this cannot be considered a surrogate indicating a condition of refractoriness to infection." (PMID 33188579, 2021). "However, at higher concentrations of TMPRSS2 plasmid, TMPRSS2 did not enhance infection, perhaps due to excessive protease activity." (PMID 34797899, 2021). "In absence of TMPRSS2 cleavage, the membrane‐bound S2 protein containing the fusion peptide of the incoming virus particle is proteolysed by cathepsin L in acidic endosomes enhancing membrane fusion and infection." (PMID 34787897, 2021). "Interestingly, infection with low SARS-CoV-2 titers induces a downregulation of NRP1 and ACE2 but an upregulation of TMPRSS2 expression in alveolar epithelial cells illustrating how multiple factors affect SARS-CoV-2 susceptibility and contribute to SARS-CoV-2 spread in the distal lung." (PMID 34026781, 2021). "Upon infection, soluble ACE2 enzymatic activity in nasopharyngeal swabs may increase in some patients, probably due to the infection itself and/or the activity of sheddase ADAM17 and TMPRSS2." (PMID 34578296, 2021). "Consistent with the finding that enzalutamide could not reduce TMPRSS2 expression in H2126 cells, enzalutamide did not inhibit infection of either H2126 cells or AR-negative Calu-3 cells by SARS-CoV-2-S." (PMID 33558541, 2021). "Indeed, SARS-CoV-2 and T403R RaTG13 S-mediated VSVpp infection of ACE2-A549 cells was efficiently inhibited by the Cathepsin inhibitor E64-d but not by the TMPRSS2 inhibitor Camostat mesylate." (PMID 34824253, 2021). "Upon infection, the S glycoprotein binds to the human angiotensin converting enzyme-2 (ACE-2) receptor located mainly on the alveolar cells of the respiratory tract following the entry of the virus particles inside the host cells by the action of human transmembrane serine protease 2 (TMPRSS2)." (PMID 35082779, 2021). "The cell type at the core of our study is very important in this context, since these cells express little ACE2 and TMPRSS2 at baseline and may be shielded from distal lung (severe) infection with SARS-CoV-2 in the absence of IAV infection." (PMID 33419885, 2021). "Similarly, the Furin and TMPRSS2 inhibitors showed no obvious inhibition on the two pangolin coronaviruses, while the Cathepsin L inhibitor had an obvious inhibitory effect on the infection of 293T-hACE2 cells with PCoV-GD and PCoV-GX." (PMID 33824288, 2021). "During infection, spike protein of SARS-CoV-2 compared to SARS-CoV displays 10–20 times greater affinity for its cognate host cell receptor, angiotensin-converting enzyme 2 (ACE2), leading proteolytic cleavage of S protein by transmembrane protease serine 2 (TMPRSS2)." (PMID 33917481, 2021). "In the lung cultures, where both TMPRSS2 and Cathepsin B/L are expressed, providing the virus with the ability to fuse both at the cell surface and in endosomes, hydroxychloroquine did not inhibit the infection significantly." (PMID 34608167, 2021). "Indeed, mice lacking TMPRSS2 have a defect in virus replication in the respiratory tract and are highly resistant to A/Narita/1/2009 infection." (PMID 34145279, 2021). "On the one hand, this could be due to the biological function of TMPRSS2 as a mediator of cell entry for SARS-CoV-2, so that differences in protein function might only influence the infection risk, rather than the course of the disease." (PMID 33968142, 2021). "Importantly, P. aeruginosa infection increased TMPRSS2 mRNA expression over time in CF but not in non-CF primary hAECs, whereas the infection did not affect ACE2 and FURIN expression." (PMID 34950129, 2021). "S2P6 completely neutralized infection of TMPRSS2-positive Vero-E6 cells but was less effective in inhibiting infection of Vero-E6 cells lacking TMPRSS2, which suggests that S2P6 binding might be reduced at endosomal pH." (PMID 34344823, 2021).
infection (continued). "In contrast, camostat, an inhibitor of the plasma membrane protease TMPRSS2, was active in Calu-3 cells but not Huh7.5 and Vero E6 cells, further highlighting the importance of understanding the translatability of a cellular model of infection." (PMID 33596266, 2021). "Moreover, the observations that IFNs induce ACE2 gene expression prompts for an urgent detailed analysis of how key effectors of the immune system regulate the ACE2, TMPRSS2 and CTSB/L genes and hence, tropism and infection rates of the virus in targeted human tissues." (PMID 33435929, 2021). "Notably, only A549-ACE2 generated with the lentiviral construct were permissive for infection in the absence of TMPRSS2, which is why we only employed one cell clone that expresses ACE2 alone in subsequent experiments." (PMID 33918670, 2021). "The incremental expression of ACE2 and TMPRSS2 may explain the increased infection rate in smokers compared with nonsmokers." (PMID 33706759, 2021). "However, this entry inhibition plateaued at 90% of maximal infection, and the remaining 10% is nearly equivalent to the raw RLU values seen with bulk 293Ts stably expressing ACE2 alone, suggesting a TMPRSS2-independent mechanism of entry." (PMID 33593976, 2021). "First, due to the limitation by using pseudotyped particles but not live virus in this study, we have to made a careful conclusion that TMPRSS2 could enhance the WIV1 entry rather than infection or replication." (PMID 32602823, 2020). "When we used low, medium or high mean expression levels of Cathepsin B/L in our calculations, with the TMPRSS2 expression level unaltered, we found that the extent of infection increased in the absence of drugs from ~2960 cells/ml at low to ~5390 cells/ml at high Cathepsin B/L expression." (PMID 33290397, 2020). "The need for clustering of ACE2 and TMPRSS2 within organized domains in lipid rafts for viral entry could help explain some of the seemingly discrepant reports that increased ACE2 could facilitate infection or actually protect against infection." (PMID 33042029, 2020). "Since both proteins are required for infection of host cells, and since our analyses clearly support suggestions of conserved binding of S-protein:ACE2 across animal species, we decided to analyse whether the TMPRSS2 was similarly conserved." (PMID 33020502, 2020). "Camostat can inhibit in vivo infection by SARS-CoV and other pneumoviruses known to utilize TMPRSS2; therefore, the drug could be a suitable antiviral candidate for drug repurposing as component of a drug combination, to prevent infections in the lungs by SARS-CoV-2." (PMID 32784899, 2020). "Cleavage and shedding of ACE2 by ADAM17 prevents the action of TMPRSS2 to facilitate viral entry and in addition the soluble shed ACE2 can still bind to the viral S-protein and hence can compete with cell surface binding and protect tissues from infection acting as a decoy receptor." (PMID 33042029, 2020). "However, in the presence of tet to induce LY6E expression, the TMPRSS2-enhanced infection of SARSpp, but not SARS-CoV-2pp, MERSpp, and 229Epp, was significantly diminished." (PMID 32641482, 2020). "TMPRSS2 and ACE2 help the virus to enter into the cells; however, development of strategies to inhibit these proteins may potentially be utilized for therapeutic purposes aimed at preventing viral entry and consequent severity of the infection." (PMID 33228225, 2020). "Studies of SARS-CoV, which also employs ACE2/TMPRSS2-mediated entry, have demonstrated that infection does not always result in production of interferons in macrophages and dendritic cell, and significantly delayed expression of type II or III interferon in lung cells." (PMID 32898168, 2020). "We also demonstrated that deletion of Tmprss2 slightly reduced body weight loss and mortality in mice after H3N2 virus infection compared to those for wild-type mice but did not protect mice from lethal infections." (PMID 26889029, 2016).
infection (continued). "However, our data demonstrate that a significant decrease in the expression of ACE2 and TMPRSS2 by a promising prophylactic candidate may not translate to infection prevention." (PMID 38886986, 2024). "Recent studies have highlighted that alternate receptors may be used for SARS-CoV-2 entry to the cells of the CNS, with neuropilin-1, CD147 and DPP4 reported as potential SARS-CoV-2 entry factors for astrocytes, and that TMPRSS2 is not required for infection of neurons." (PMID 38995681, 2024). "However, no protease tested promoted the infection of B236 except for TMPRSS2." (PMID 38838469, 2024). "Thus, the Omicron F375 unique residue impacts infection regardless of TMPRSS2." (PMID 37243215, 2023). "Finally, the cellular infection of SARS-CoV-2 while dependent on TMPRSS2 and furin activity, is quite different from that of SARS-CoV-2 bearing Omicron variants, as the viral entry of the latter seems to be independent of TMPRSS2 activity and/or levels." (PMID 36851576, 2023). "Therefore, it is possible that TMPRSS2 function is not mandatory for normal mouse development and in vivo cell viability, but could play a role in challenging situations, like infections or just during in vitro culturing and differentiation of cells." (PMID 36830955, 2023). "Additionally, the S protein containing S1 and S2 domains can be cleaved by Furin or transmembrane serine protease 2 (TMPRSS2) to accelerate the virus-cell membrane fusion and increase the viral tropism to organs, which may justify why SARS-CoV-2 has a higher infection rate than SARS-CoV." (PMID 36687524, 2022). "Thus, extreme cases could exceed the interquartile range provided by an additional two orders of magnitude, reaching values of 1013 viral particles in a single person at the peak of infection, while up to 10% of the cells expressing both ACE2 and TMPRSS2 are infected." (PMID 34083352, 2021). "Indeed, the fact that TMPRSS2, but not ADAM17 expression was downregulated upon infection might indicate the prominent role of TMPRSS2 in the context of SARS-CoV-2 infection." (PMID 34578296, 2021). "Although to date ACE2/TMPRSS2 function in SARS-CoV-2 entry has been widely demonstrated, few studies have suggested that other cellular proteases and cofactors might have a role, especially in the case of the infection of cells expressing low ACE2/TMPRSS2 levels." (PMID 34209845, 2021). "Furthermore, several other factors may contribute to this balancing act: (A) Transmembrane protease serine 2 (TMPRSS2) primes the S protein of the SARS-CoV-2 virus to bind to its receptor, angiotensin-converting enzyme 2 (ACE2), during infection and ACE2 is an IFN-stimulated gene." (PMID 34276349, 2021). "Whether TMPRSS2 and ACE2 colocalize on the hair-like extensions of ciliated cells is worth considering because such a coincidence at the most accessible apical locations would likely promote highly efficient virus binding, virus–cell fusion, and subsequent infection." (PMID 33901166, 2021). "Upon intranasal infection of mice with mouse-adapted PR8M (A/PuertoRico/8/34 H1N1 Münster variant,), wild type mice lost weight significantly after infection and 50% of infected mice died, whereas Tmprss2 knock-out mice did not exhibit body weight loss and showed no signs of disease." (PMID 24348248, 2013). "In conclusion, in the absence of NA pretreatment, TMPRSS2 fully enabled UCD infection, significantly enhanced UG-FH8 infection, and slightly promoted ABA infection." (PMID 41505483, 2026). "If ACE2 is present without TMPRSS2, then the BBB internalizes the virion, anchored by ACE2 binding, and produces a direct infection through the secondary targets of the endosome—likely the Golgi body." (PMID 38793666, 2024). "To investigate this in more detail, we performed infection assays in engineered cells promoting ACE2-mediated entry with and without TMPRSS2 coexpression." (PMID 38814864, 2024).